ABI3BP (ABI family member 3 binding protein)
Synonyms: Tarsh; NeshBP; DKFZP586L2024
Tractability: Antibody: UniProt places it where antibodies can reach, with high confidence; UniProt predicts a signal peptide or a membrane-spanning region; its Gene Ontology location is reachable by antibodies, with medium confidence.
Gene: Protein-coding gene on chromosome 3 (100,749,155 to 100,993,515, reverse strand). Ensembl gene ENSG00000154175.
Subcellular location: Secreted
Gene Ontology:
Molecular function: extracellular matrix structural constituent
Cellular component: extracellular matrix; extracellular region; non-collagenous component of interstitial matrix
Genetic constraint (gnomAD): Loss-of-function variants: 154 observed, 186.32 expected, observed/expected ratio (o/e) 0.83, 90% interval 0.72 to 0.94. The upper end of that interval is the gene's LOEUF score, 0.94, which puts it in group 4 of 6, group 1 being the genes least tolerant of losing a copy. Missense variants: 1,675 observed, 1,739.2 expected, observed/expected ratio (o/e) 0.96, 90% interval 0.92 to 1. Synonymous variants: 584 observed, 588.79 expected, observed/expected ratio (o/e) 0.99, 90% interval 0.93 to 1.06.
Homologues: Orthologues: chimpanzee ABI3BP (98% identical), macaque ABI3BP (95% identical), dog ABI3BP (84% identical), rabbit ABI3BP (81% identical), pig ABI3BP (79% identical), rat Abi3bp (70% identical), mouse Abi3bp (69% identical), guinea pig ABI3BP (50% identical), tropical clawed frog abi3bp (33% identical), zebrafish abi3bpb (20% identical), zebrafish abi3bpa (18% identical). Paralogues in human: FNDC1 (19% identical).
Diseases named in the same sentence as ABI3BP in open-access papers:
ABI3BP is named in the same sentence as 46 diseases in open-access papers, as found by Europe PMC text mining. Sharing a sentence is not in itself a finding about the gene and the disease. The quoted sentences say what the papers report.
gallbladder cancer (8 papers, 2019 to 2023). "Moreover, the loss of ABI3BP expression may be functionally involved in the pathogenesis of several types of cancer such as gallbladder cancer and esophageal cancer." (PMID 36193505, 2022). "For example, our previous study showed that lncRNA MALAT1 enhanced the proliferative capability of gallbladder cancer cells by epigenetically recruiting the enhancer of EZH2 to the ABI3BP promoter region." (PMID 37564197, 2023). "According to previous studies, miR-183 participates in the pathogenesis of ESCC, while ABI3BP is related to gallbladder cancer, thyroid tumors, and lung cancer." (PMID 32774142, 2020). "Similarly, we discovered that forced expression of ABI3BP in gallbladder cancer decreased tumor activity." (PMID 37197424, 2023). "ABI3BP is a protective factor in gallbladder cancer, esophageal carcinoma, and lung carcinoma." (PMID 34497681, 2021). "Taking transcription regulation as an example, MALAT1 can recruit EZH2 to the promoter region of ABI3BP (ABI family member 3 binding protein) and then promote H3K27me3, thereby inhibiting the transcription of ABI3BP and ultimately promoting the metastasis of gallbladder cancer." (PMID 33520725, 2020). "Previous studies have shown that by inhibiting ABI3BP, the long non-coding RNA, MALAT1, stimulates the proliferation of gallbladder cancer cells and prevents aging." (PMID 36744181, 2022).
esophageal cancer (7 papers, 2020 to 2023). A primary or metastatic malignant neoplasm involving the esophagus. "ABI Family Member 3 Binding Protein (ABI3BP) is an extracellular matrix protein that affects the carcinogenesis of lung and esophageal cancer." (PMID 37197424, 2023). "It has been reported that elevated ABI3BP expression in esophageal cancer cells inhibits cell apoptosis and promotes cell proliferation." (PMID 37197424, 2023). "ABI3BP downregulation by miR-183 suppressed proliferation, activity, and migration of human esophageal cancer cells." (PMID 35418993, 2022). "MicroRNA-183 consumes ABI3BP and also promotes the growth of esophageal cancer." (PMID 36744181, 2022).
lung carcinoma (6 papers, 2017 to 2022). "Univariate and multivariate cox regression analysis showed that elevated ABI3BP and elevated clinical stage were independent risk factors for lung cancer patients." (PMID 36744181, 2022). "The “pROC” package was used for ROC analysis, and it could be seen that the area under the diagnostic ROC curve was greater than 0.9, which indicated that ABI3BP had a good diagnostic value for lung cancer." (PMID 36744181, 2022). "First, we explore the diagnostic significance and prognostic value of ABI3BP for lung cancer." (PMID 36744181, 2022). "Down-regulation of ABI3BP expression has been found in thyroid tumorigenesis and lung cancer cell lines, and thus, deleterious mutations of ABI3AP might contribute the tumour development." (PMID 29213343, 2017). "Therefore, it can be concluded that the hub genes related to ABI3BP may be involved in immune cell infiltration through mutation, thus affecting the progression of lung cancer." (PMID 36744181, 2022). "Based on these results, ABI3BP may be a gene associated with lung cancer growth." (PMID 36744181, 2022). "Then, QUANTISEQ analysis showed a significant positive correlation between ABI3BP and T cell regulation (Tregs) in lung cancer." (PMID 36744181, 2022). "Thirdly, ABI3BP was discovered to be related with immune infiltration in patients with lung carcinoma, however subgroup studies of immunity would have increased the data relevance." (PMID 36744181, 2022). "We found that in lung cancer, ABI3BP was significantly positively correlated with B memory cells, CD4+ T memory cell rest, Tregs, B cell, T cell, CD4+ T, myeloid dendritic cell activation, and endothelial cells." (PMID 36744181, 2022). "The amount of expression of ABI3BP in regular lung tissues was substantially greater than in lung cancer tissues." (PMID 36744181, 2022). "We now know more about the connection between ABI3BP and lung cancer thanks to this research, however, there are yet some limitations." (PMID 36744181, 2022). "This study utilized TCGA, GEPIA, UALCAN, HPA, Genecards, TIMER, TISIDB, STRING, Kaplan Meier plotter statistics, The Cancer Immunome Atlas, and R package to explore the role of ABI3BP in lung cancer." (PMID 36744181, 2022). "In fact, the expression level of ABI3BP mRNA was markedly decreased in human lung cancer cell lines and clinical samples." (PMID 32774142, 2020). "In the previous study, we found that ABI3BP showed significant differences in prognosis and clinical data, so we further explored whether ABI3BP can be an independent prognostic factor for lung cancer patients." (PMID 36744181, 2022). "In addition, multivariate regression analysis further confirmed that ABI3BP expression and Stage were independent prognostic factors for OS in lung cancer patients." (PMID 36744181, 2022). "Simultaneously, ABI3BP was substantially related with many immune cell marker sets for lung cancer." (PMID 36744181, 2022). "Finally, TIMER database analysis showed that ABI3BP had the highest correlation with dendritic cell cells in lung cancer." (PMID 36744181, 2022). "Next, we explored the potential molecular mechanism of ABI3BP in lung cancer immunoinfiltration." (PMID 36744181, 2022). "Due to the significant relation of expression of ABI3BP and immune cell infiltration and prognosis of lung tumor, we then examined whether its expression affects lung cancer prognosis due to immunity invasion." (PMID 36744181, 2022). "Besides, the expression of ABI3BP has been reported to undergo decreases in lung cancer cell lines, suggesting its function as a biomarker for lung cancer progression." (PMID 31174563, 2019). "ABI3BP might be employed as a biomarker of lung cancer prognosis related with immune infiltration." (PMID 36744181, 2022). "ABI3BP might provide a novel immunotherapeutic target for lung cancer." (PMID 36744181, 2022).
lung carcinoma (continued). "These outcomes imply that ABI3BP over-expression may prevent the development of lung cancer." (PMID 36744181, 2022). "In addition, ABI3BP was reported to show decreased expression in lung cancer cell lines, suggesting that ABI3BP could be a biomarker for lung cancer progression." (PMID 32774142, 2020). "For clinical stage, mRNA expression levels of ABI3BP gradually decrease in stage I, II, and III as lung cancer progresses." (PMID 36744181, 2022).
thyroid cancer (6 papers, 2011 to 2023). "A study demonstrated that ABI3BP inhibits thyroid cancer cell viability, migration, invasion, and tumor growth." (PMID 37197424, 2023). "In thyroid cancer cells, reexpression of ABI3BP lead to reversion of the tumorigenic capacity of cells." (PMID 27096627, 2016). "ABI3BP inhibits tumor growth by promoting aging and inhibiting invasion in thyroid cancer." (PMID 36744181, 2022). "The present study investigated ABI3 expression in a large panel of benign and malignant thyroid tumors and explored a correlation between the expression of ABI3 and its potential partner ABI3-binding protein (ABI3BP)." (PMID 21223585, 2011).
thyroid tumor (4 papers, 2015 to 2024). A benign or malignant neoplasm affecting the thyroid gland. "ABI3BP recovery was highlighted as an important factor associated with thyroid tumors that inhibited tumor growth and invasion and promoted cell senescence." (PMID 32774142, 2020). "ABI3BP restoration has been highlighted as a significant factor in relation to thyroid tumors, whereby tumor growth and invasion are impeded while cell senescence is promoted." (PMID 31174563, 2019). "Notably, a significant decrease in ABI3BP expression is observed in the majority of malignant thyroid tumors." (PMID 38812032, 2024).
depression (3 papers, 2014 to 2016). "We also found that UT-Other interacts with a SNP in gene ABI3BP that was previously associated with suicide attempts among patients with depression." (PMID 28002425, 2016). "Among 1273 subjects with major depression, 6 loci had SNPs with a p value of <1 × 10−5; the minimum p value was 2.55 × 10−8 (rs2576377 in gene ABI3BP)." (PMID 27721799, 2016).
dilated cardiomyopathy (3 papers, 2019 to 2025). Cardiomyopathy which is characterized by dilation and contractile dysfunction of the left and right ventricles. "It has been documented that the level of ABI3BP among patients having heart failure in dilated cardiomyopathy is significantly reduced, and ABI3BP controls the multiplication and derivation of cardiac progenitor cells." (PMID 36744181, 2022). "We further showed that ABI3BP levels are reduced by approximately half from the left ventricular extracellular matrix in failing human hearts with dilated cardiomyopathy." (PMID 30923710, 2019). "Significant downregulation of extracellular matrix protein ABI3BP is another indicator of increased fibrosis because it promotes differentiation over proliferation, as demonstrated in Abi3bp knock-out mice after myocardial infarction and in dilated cardiomyopathy of human hearts." (PMID 41373557, 2025). "Furthermore, our study showed that ABI3BP levels were significantly reduced in failing human hearts with dilated cardiomyopathy." (PMID 30923710, 2019).
colon cancer (2 papers, 2021 to 2023). "ABI3 expression is frequently reduced or lost in most colon cancer cell lines, and interestingly, there exists a positive correlation between ABI3 and ABI3BP expression in these carcinomas." (PMID 37768206, 2023).
myocardial infarction (2 papers, 2019 to 2025). Gross necrosis of the myocardium, as a result of interruption of the blood supply to the area, as in coronary thrombosis. "Wild-type mice showed a reduction in cardiac fibrosis and improved cardiac function 1 month post-myocardial infarction compared to ABI3BP knockout mice." (PMID 30923710, 2019). "This implies that ABI3BP suppresses cardiac progenitor cell activation toward cardiac repair, but its suppression improves functional outcomes post-myocardial infarction." (PMID 30923710, 2019). "Wild-type and ABI3BP-knockout mice were subjected to myocardial infarction via coronary artery restriction, or a sham operation." (PMID 30923710, 2019). "Myocardial infarction induced c-Kit+ cardiac progenitor cells in both wild-type and ABI3BP-knockout mice, but more so in knockout mice." (PMID 30923710, 2019).
preeclampsia (2 papers, 2019 to 2022). Preeclampsia is a hypertensive disorder of pregnancy that is characterized by new-onset hypertension with proteinuria presenting after 20 weeks of gestation, and depending on mild or severe forms may initially present with severe headache, visual disturbances, and hyperreflexia. "ABI3BP genetic mutations may also be responsible for early-onset preeclampsia." (PMID 30923710, 2019). "Expression of ABI3BP of mRNA was upregulated among patients having early preeclampsia in comparison with the control group matched with late preeclampsia and gestational age." (PMID 36744181, 2022). "ABI3BP mRNA was upregulated in early-onset preeclampsia compared to late-onset preeclampsia and gestational age-matched controls." (PMID 30923710, 2019).
emphysema (1 paper, 2019). "Thus, a decrease in expression of ABI3BP appears to be protective to cigarette smoke-induced emphysema." (PMID 30923710, 2019).
hydronephrosis (1 paper, 2024). Collection of urine in the renal pelvis that results in dilatation of the renal pelvis and calyces. "Verification through the UUO model demonstrated a significant reduction in hydronephrosis and fibrosis levels in the ABI3BP−/− group." (PMID 38812032, 2024).
hydrops (1 paper, 2024). "Additionally, a unilateral ureteral obstruction (UUO) model of kidney injury in mice demonstrated evident hydrops and fibrosis in the UUO group, with significantly increased blood urea nitrogen and elevated ABI3BP expression in both blood and kidney tissues." (PMID 38812032, 2024).
lymph node metastasis (1 paper, 2022). "It was found that the expression degree of ABI3BP was related to clinical factors such as gender, age, smoking habit, clinical stage, and lymph node metastasis status." (PMID 36744181, 2022).
mesothelioma (1 paper, 2023). A usually malignant and aggressive neoplasm of the mesothelium which is often associated with exposure to asbestos. "Abnormal expression of ABI3BP accurately predicts the prognosis of patients with renal chromophobe carcinoma (KICH), mesothelioma (MESO), and pancreatic adenocarcinoma (PAAD)." (PMID 37197424, 2023).
osteoarthritis (1 paper, 2022). A noninflammatory degenerative joint disease occurring chiefly in older persons, characterized by degeneration of the articular cartilage, hypertrophy of bone at the margins and changes in the synovial membrane. "For ABI3BP we detected increased inclusion of the exon cassette spanning the region (chr3:100808235–100846372) in high-osteoarthritis grade cartilage." (PMID 35088088, 2022).
osteochondropathy (1 paper, 2016). "In humans, Polymorphisms in ABI3BP are associated with increased risk of osteochondropathy, and mice lacking Abi3bp have profound defects in MSC differentiation to bone and fat." (PMID 27042394, 2016).
small cell lung carcinoma (1 paper, 2022). Small cell lung cancer (SCLC) is a highly aggressive malignant neoplasm, accounting for 10-15% of lung cancer cases, characterized byrapid growth, and early metastasis. "Initially, the biological relevance of ABI3BP in LUAD and LUSC was examined in detail, but the expression and prognostic score of ABI3BP in small cell lung carcinoma were not examined." (PMID 36744181, 2022).
squamous cell carcinoma (1 paper, 2021). A carcinoma arising from squamous epithelial cells. "ABI3BP was significantly downregulated in cSCC compared with that in the normal skin in one previous study and similarly downregulated in the esophagus with squamous cell carcinoma compared with that in the normal esophagus." (PMID 33482222, 2021).
cancer (22 papers, 2011 to 2025). A tumor composed of atypical neoplastic, often pleomorphic cells that invade other tissues. "This shows that genes linked to ABI3BP are engaged in cancer-associated functional states and govern the immune responses of tumor cells, influencing the prognosis of patients." (PMID 37197424, 2023). "The results of the MCPCOUNTER and EPIC algorithms were similar: Myeloid dendritic cells and Endothelial cells were associated with the strongest positive correlation between ABI3BP expression in various cancers was found." (PMID 37197424, 2023). "Afterward, we determined possible correlations on immune-associated pan-cancer genes by ABI3BP expressions." (PMID 37197424, 2023). "The ABI3BP gene, encoding mediators of senescence, has previously been implicated in cancer, immunity, and cardiovascular risk." (PMID 38001857, 2023). "We also provided evidence that ectopic expression of ABI3BP in ABI3BP-deficient carcinoma cell lines inhibited in vitro and in vivo cell growth." (PMID 21223585, 2011). "Our results show that ABI3BP might be employed as a molecular biomarker to predict prognosis, treatment susceptibility, and immunological response in patients with pan-cancer." (PMID 37197424, 2023). "A correlation between ABI3BP expression and the amount of infiltration of several immune-related cells in pan-cancer was determined by Immune Score, Stromal Score, and Estimated Score." (PMID 37197424, 2023). "In certain cancer patients, ABI3BP was identified as an independent prognostic factor, and its high expression was linked with a better prognosis." (PMID 37197424, 2023). "In order to comprehend the synergistic effect of ABI3BP on cancer, we screened 20 ABI3BP-related genes as a gene set for a comprehensive study." (PMID 37197424, 2023). "Based on the obvious relationship between ABI3BP and immune response, we performed a pan-cancer analysis of the relationship between ABI3BP expression and the level of immune infiltration according to the TIMER database." (PMID 37197424, 2023). "This study analyzed the differences in ABI3BP mRNA and protein expression levels in pan-cancer tissues using the TCGA, GTEx, CCLE, and HPA databases." (PMID 37197424, 2023). "The xCell algorithm also provided the corresponding analysis: the strongest negative correlation between T cell CD4+ Th1, Th2 and T cell CD4+ central memory cells and the presence of ABI3BP expression in various cancers." (PMID 37197424, 2023). "In conclusion, our findings demonstrate that ABI3BP expression levels vary widely among human cancers and correlate with clinical case characteristics and prognosis in pan-cancer patients." (PMID 37197424, 2023). "The close relationship between ABI3BP and patient prognosis suggests that ABI3BP is involved in regulating cancer-related functional status." (PMID 37197424, 2023). "This work contributes to our knowledge of the relationship between ABI3BP and pan-cancer, although it has several drawbacks." (PMID 37197424, 2023). "SLIT3, ABI3BP, MYOCD, PGM5, TNXB and DNAH9 are strongly associated with cancer initiation and progression." (PMID 36451444, 2022). "Using the repository of the TIMER database the expression of mRNA of ABI3BP in human cancer had been examined." (PMID 36744181, 2022). "ABI3BP has been reported to be downregulated in a number of cancers with supporting evidence that its expression promotes cellular senescence." (PMID 34874125, 2022). "Studies have confirmed the tumor-suppressive effect of ABI3BP, suggesting that the ectopic expression of ABI3BP can impair the growth characteristics of cancer cells and induce senescence." (PMID 32774142, 2020). "ABI3BP is best known for is its role in multiple forms of cancer, acting as a tumor suppressor via promotion of cellular senescence." (PMID 30923710, 2019). "The results confirmed that the cancer prevention effects triggered by restored ABI3BP and depleted MALAT1 as evidenced by suppressed cell growth and enhanced cell senescence." (PMID 31174563, 2019).